MCAM (melanoma cell adhesion molecule)
Diseases named in the same sentence as MCAM in open-access papers (continued):
Sharing a sentence is not in itself a finding about the gene and the disease.
tumor (continued). "DOCK11 showed significantly lower levels in tumor datasets, while MCAM, MYO10, and WASF3 exhibited significantly higher levels in tumor datasets, compared with the normal group." (PMID 34128858, 2021). "Another tentative target of tumor vasculature is CD146 (melanoma cell adhesion molecule, MCAM), an adhesion molecule present on many tumors and on vascular endothelial and smooth muscle cells." (PMID 33802812, 2021). "We observed for the first time a patient subgroup that is characterized by a higher expression of MUC14/EMCN, MUC18/MCAM, and MUC15 in their tumor tissue." (PMID 33182511, 2020). "In their study, tumor myofibroblasts were identified based on the expression of α-SMA, melanoma cell adhesion molecule (MCAM), myosin light chain kinase (MYLK), and myosin light chain 9 (MYL9)." (PMID 31106200, 2019). "CD146 (also known as MCAM, S-endo-1, P1H12, and MUC18) was identified as a novel endothelial biomarker for angiogenesis in the tumor progression of several malignancies." (PMID 31303863, 2019). "The possible role of EMT in tumor propagation was substantiated by the expression of a variety of markers described to be involved in EMT, such as Zeb1 and CD146/MCAM." (PMID 29171037, 2018). "CD146, also known as MCAM or MUC18, is a membrane calcium-independent glycoprotein adhesion molecule, which was identified as a tumor angiogenesis marker." (PMID 28626293, 2017). "Sixteen primary matched tumor and serum were analyzed by quantitative methylation specific PCR (QMSP) to determine analytical and clinical sensitivity of the genes tested (SSBP2, MCAM, ERα, ERβ, APC, CCND2, MGMT, GSTP1, p16 and RARβ2)." (PMID 28147335, 2017). "MCAM or melanoma cell adhesion molecule (CD146) is a VEGFR2 co-receptor, has implications in tumour angiogenesis and is found to be upregulated in a wide range of different cancers." (PMID 26620208, 2016). "CD146, also known as melanoma cell adhesion molecule (MCAM) or S-Endo-1 antigen, is a component of the endothelial junction involved in the control of cell cohesion and tumor angiogenesis." (PMID 24734218, 2014). "A total of 15 genes (AIM1, ARF, CCNA1, MGMT, hMLH1, PGP9.5, S100A2, APC, RAR-β2, ER-α, ER-β, MCAM, VGF, FKBP4 and SSBP2) were analysed for promoter methylation using QMSP in 57 tumour samples, comprising 43 SEs and 14 NSEs, and 23 NT samples." (PMID 22068818, 2012). "In contrast to E-cadherin, another type of adhesion molecule, the immunoglobulin superfamily (including NCAM, MCAM, ALCAM and L1CAM, among others), is often highly expressed in metastatic tumour tissues." (PMID 22610942, 2012). "Inhibition of MCAM using a blocking monoclonal antibody led to downregulation of p38 MAPK phosphorylation, the suppression of NF-κB activation, and a decrease in tumour growth, possibly due to cell death through apoptosis." (PMID 22272201, 2012). "Additionally, the accumulation of misfolded AAT proteins triggers the expression of cyclin D1 and melanoma cell adhesion molecule (MCAM) gene, both of which are involved in regulating cell growth and promoting tumor development." (PMID 40833357, 2026). "Non-tumor components included endothelial cells (expressing VWF, CDH5, ECSCR, SLCO2A1, and MYCT1), pericytes (marked by RGS5, MCAM, and PDGFRB), normal oligodendrocytes (showing PTGDS, MBP, TF, and MOG expression), and TAMs (identified by CD14, AIF1, FCER1G, FCGR3A, TYROBP, and CSF1R)." (PMID 41394801, 2025). "Notably, these markers have previously been linked to different cell types, including endothelial cells (CD44, ENG, F3, MCAM, and ITGB1), immune cells (CD14, CD44, CSPG4, ENG, HLA-DR/DP/DQ), and neuronal cells (NCAM1), as well as astrocytes and tumor cells." (PMID 39594703, 2024). "The polar accumulation of F-actin co-localizes with the β1-Integrin, melanoma cell adhesion molecule (MCAM) and intercellular adhesion molecule-1, which may contribute to the improved adhesion of tumor cells." (PMID 37369706, 2023).
tumor (continued). "In addition to the membrane-anchored MCAM/MUC18/CD146, a soluble form—sCD146/MCAM/MUC18—generated by metalloproteases proteolytic cleavage is mainly involved in tumor angiogenesis." (PMID 32548126, 2020). "CD146, also known as melanoma cell adhesion molecule (MCAM), member of the immunoglobulin (Ig) superfamily, cooperates in different biological processes including tumor metastasis, lymphocyte activation, and morphogenesis during development, and tissue regeneration." (PMID 28241866, 2017). "On the other hand, when possible, molecular MCAM/MUC18 expression was correlated to the immunohistochemical negative staining on the primary tumours." (PMID 24902661, 2014). "By Spearman correlation test, eight genes (AIM1, CCNA1, MCAM, PGP9.5, hMLH1, ARF, VGF and APC) showed to be independent of each other and were selected to be included in a logistic regression model, which predict the probability of tumour." (PMID 22068818, 2012). "Subsequently, we assessed the infiltration levels of each fibroblast subtype across different tissues, noting that FAP+ fibroblasts predominantly resided within tumor regions while MCAM+ fibroblasts were notably observed in normal region indicating their biological heterogeneity." (PMID 40438108, 2025). "MCAM has also been described as a co‐receptor for several growth factor receptors such as VEGFR2 or PDGFR‐β or inflammatory mediators such as S100A8/A9, and may thereby promote cell growth and simulate tumour vascularisation." (PMID 39945026, 2025). "How MCAM promotes tumour invasion and metastatic spread is currently not fully understood." (PMID 39945026, 2025). "However, MCAM expression was not significantly different between the primary tumour and the corresponding metastasis." (PMID 37138793, 2023). "However, it seems plausible that the majority of malignant cells with an epithelial phenotype silence MCAM by promoter methylation leaving a minority of cells which induce MCAM expression upon EMT; this highlights the need to explore tumour heterogeneity in greater detail." (PMID 37138793, 2023). "Some of the most promising candidates include melanoma cell adhesion molecule (MCAM), stem cell factor (SCF), HSP-27, and vimentin since these proteins have a crucial role in normal, as well as pathological cell functions and can be found within the primary tumor." (PMID 24078811, 2013). "Also, Tregs from NI ad I TDLN share CD58, ITGAM, MCAM, CEACAM4, SELPLG, and HMMR expression, which could ensure recirculation among TDNLs; and Tregs from I TDLN and tumor Tregs share ICAM1 expression, which could be responsible for the migration among tissues with presence of tumor cells." (PMID 32601304, 2020). "For the remaining genes (SSBP2, MCAM, ERα, ERβ, CCND2, MGMT, GSTP1 and p16) methylation in serum DNA was always corresponding to methylation of tumor DNA, while methylation of tumor DNA was not always corresponding to methylation of serum DNA." (PMID 28147335, 2017). "To investigate the molecular determinants of the different angiogenic patterns, we studied the expression of various genes involved in the control of tumor angiogenesis but no relevant variations (data not shown) were observed for several of these (FGF2, PECAM1, MCAM, COX2)." (PMID 28903354, 2017).
cancer (180 papers, 2008 to 2026). A tumor composed of atypical neoplastic, often pleomorphic cells that invade other tissues. "MCAM upregulation in cancer cells is associated with changes in EMT marker levels, such as downregulation of the epithelial marker E-cadherin and upregulation of mesenchymal markers such as vimentin, fibronectin, β-catenin, and N-cadherin." (PMID 41388158, 2025). "We confirmed the differential upregulation of previously known genes in such as SCIN, CALD1 and MCAM, which have been associated with aggressive, basal-like phenotype and in acquired drug resistance in cancer." (PMID 40946111, 2025). "Over time, MCAM expression has been identified in various cancers, but the conclusions of most studies indicate that the presence/overexpression of MCAM is strongly associated with metastasis and a poor disease prognosis." (PMID 41388158, 2025). "Increased MCAM expression is associated with poor prognosis, increased metastasis, and recurrence rate in various cancers." (PMID 39554906, 2024). "CD146, also known as melanoma cell adhesion molecule (MCAM), is expressed in numerous cancers and has been implicated in the regulation of metastasis." (PMID 37138793, 2023). "KDM3A transcriptome analysis revealed, in addition to Ets1 and MCAM, other genes previously implicated in the promotion of aggressive cancer properties, including the genes FYN, AXL, LOXL2 and PLAU." (PMID 32577157, 2020). "While MCAM, VE-cadherin, and Endoglin contribute to angiogenesis, and angiogenesis can be therapeutic in the context of repair after injury, VE-cadherin- and Endoglin-associated angiogenesis is more often implicated in cancer angiogenesis." (PMID 39518030, 2024). "MUC18/MCAM/CD146 is expressed in cancer-associated fibroblasts that are enriched in PDAC stroma." (PMID 33182511, 2020). "GO analysis of this group shows representation of biological pathways related to cell proliferation and motility, and genes that have been previously implicated in FP‐RMS pathogenesis (MAPK1, ILK, MCAM), as well as numerous other cancer‐promoting genes (based on literature survey)." (PMID 32697014, 2020). "In cancer cells MCAM has been linked with Id1 expression, which is a known inhibitor of myogenesis." (PMID 28923978, 2017). "Under pathological conditions such as inflammation and tumorigenesis, MCAM is upregulated in related cells and is considered a reliable marker for many types of cancer, and MCAM overexpression is associated with the initial development or metastasis of most cancers." (PMID 40713600, 2025). "Given the distinct pro-tumorigenic role of MCAM in cancer cells our attention turned to its role in GC, where MCAM expression is also highly upregulated." (PMID 40924339, 2025). "This review synthesizes current understanding of MCAM’s multifunctional roles, its bidirectional influence in health and disease, and its potential as a therapeutic target in cancer." (PMID 41388158, 2025). "CD146, or melanoma cell adhesion molecule, is known to promote the loss of cell–cell contacts, EMT, and enhanced cell motility, contributing to the invasive potential of cancer cells." (PMID 40001942, 2025). "In pan‐cancer analysis, MCAM gene expression was significantly lower in various common cancers compared to normal tissue, including colon, lung, and prostate." (PMID 40042109, 2025). "This intense expression was consistently present in multiple poorly differentiated specimens, indicating a robust upregulation of MCAM in more aggressive cancer phenotypes." (PMID 40924339, 2025). "The hot spot mutation P459T of NTN1 occurred in three patients with two cancers (STAD and READ), and the hot spot mutation R267C/G/H of MCAM occurred in four cancers (STAD, BLCA, UCEC, and LUSC)." (PMID 41407823, 2025). "The literature also indicates that MCAM plays a role in promoting cancer in various types of cancers." (PMID 40713600, 2025). "These samples displayed strong and widespread MCAM staining in the membrane and cytoplasm of cancer cells." (PMID 40924339, 2025).
cancer (continued). "Melanoma cell adhesion molecule (MCAM) is a cell-surface protein overexpressed in a variety of pediatric cancers, including NB." (PMID 39554906, 2024). "We found significantly increased methylation in this region of the MCAM gene in cancer compared to normal tissue." (PMID 37138793, 2023). "In contrast, reduced MCAM expression has been revealed to stimulate tumorigenesis and cancer stemness in CRC by activating the Wnt/β-catenin signaling pathway." (PMID 36739428, 2023). "PI3K/Akt/SOX2/CREB1 signaling and glycolytic shifts also participate in MCAM-guided chemoresistance in cancer cells." (PMID 37701037, 2023). "MCAM, also known as CD146, is a cell surface adhesion molecule that is widely declaimed to facilitate cancer progression and metastasis." (PMID 36340580, 2022). "We concluded that miR-640 inhibition enhanced MCAM expression and thus attenuated the anti-cancer effects of MCAM knockdown." (PMID 36340580, 2022). "Two additional atypical endothelial mucins (MUC14/EMCN and MUC18/MCAM) have been described in cancer." (PMID 33182511, 2020). "The level of MCAM expression correlates with an aggressive and invasive phenotype of cancer and as such serves as a marker for poor prognosis." (PMID 32204304, 2020). "Throughout the study, the MLV Gag refers to VLPs obtained by expression of MLV Gag protein without any recombinant cancer antigen, and MART1, TRP1, MAGEA4, MAGEA10 and MCAM mark the VLPs carrying respective cancer antigens." (PMID 27403717, 2016). "Increased stromal expression of MCAM parallels metastatic potential in osteotropic cancers, including PCa and MCa." (PMID 25485970, 2014). "Since MCAM is involved in the development and progression of cancer through several mechanisms, it represents a potential target in the cancer treatment with less possible development of resistance to the therapy." (PMID 25350580, 2014). "Moreover, MCAM knockdown correlated with reduced migration, adhesion, and proliferation of different cancer cells." (PMID 41388158, 2025). "In particular, we found that in the lung a trend toward an increase in VIM, as well as of the CDH5, MCAM, and MMP2 mRNAs associated with the metastasis-derived cancer cell lines, whereas the MMP9 gene seemed to be mainly related to the mesenchymal phenotype of these cells." (PMID 40332096, 2025). "Beyond cancer, anti-MCAM antibodies have applications in other diseases." (PMID 41388158, 2025). "Additionally, resume of MCAM expression reversed the inhibitory effects of SOX18‐downregulation on cancer metastasis, whereas downregulation of MCAM abrogated the enhanced metastatic capacity in SOX18‐overexpressing cancer cells." (PMID 40778650, 2025). "Taken together, MCAM overexpression may inhibit plasma cell infiltration in cancer tissues, weakening antitumour immune response." (PMID 40778650, 2025). "Finally, MCAM seems to be strongly involved in cancer progression, at the same time being the protein of interest in the context of antitumor therapy." (PMID 41388158, 2025). "In addition, we demonstrate that NOX1, ADAM17, and membrane MCAM are present in a multiprotein complex in endothelial and cancer cells and that long-term treatment with NOX1 inhibitor partially decreases ADAM17 expression and the generation of sMCAM." (PMID 38137406, 2023). "Cluster of differentiation 146 (CD146), also known as melanoma cell adhesion molecule (MCAM) or mucin 18 (MUC18), is a member of the immunoglobulin (Ig) superfamily and is reported to be involved in various pathological conditions, including cancer and chronic inflammatory diseases." (PMID 37308559, 2023). "Despite all the reports related to soluble MCAM functions in cancer, many questions remain unanswered, especially those concerning the functional relevance of sMCAM and the mechanism behind its shedding from cancer cells and vascular endothelium." (PMID 38137406, 2023). "Soluble MCAM is a pro-angiogenic factor, produced by endothelial and MCAM-positive cancer cells." (PMID 38137406, 2023).
cancer (continued). "Overall, the oncogenic effect of MCAM in diverse cancers has been verified." (PMID 36340580, 2022). "The possible roles of MCAM in other cancers were further investigated using the GEPIA2 database." (PMID 34961985, 2022). "Knowing that MCAM is involved in the development and progression of cancer disease through several pathways, it represents a good target in combined modalities (irradiation, chemotherapy) to treat cancer, with less possibility of resistance to treatment." (PMID 32204304, 2020). "Preclinical studies have shown a silencing approach to target MCAM as valuable in cancer treatment." (PMID 32204304, 2020). "As MCAM and β1-integrins are also involved in cancer metastasis, our data might provide a mechanistic link between these molecules and disease progression also in that context." (PMID 33381120, 2020). "Our microarray results suggest that MOB1 in NSCLC could predominantly regulate the expression of genes promoting cancer invasiveness such as MCAM and ADAM12." (PMID 32841529, 2020). "MCAM expression by cancer cells has been reported in most cancer types." (PMID 25485970, 2014). "The expression of MCAM is subject to complex regulatory mechanisms, including epigenetic modifications and noncoding RNAs, which could influence its activity in various types of cancer." (PMID 41388158, 2025). "Therefore, MCAM-mediated homophilic interaction between cancer and BM stromal cells may represent a possible molecular mechanism of osteotropism." (PMID 25485970, 2014). "The dysregulation of cell migration, adhesion and invasion regulators, such as MCAM/CD146, ALCAM/CD166, CAR/CXADR, EFNA1, LAMA5, CD73/NT5E and integrins, contributes to cancer progression and metastasis." (PMID 40314078, 2025). "We found that NTN1, DCC, DSCAM, MCAM, and UNC5D were methylated in many cancers, of which UNC5D was the most prominent." (PMID 41407823, 2025). "Receptors of S100A9, including TLR4, RAGE, CD147, MCAM and NPTN are expressed in multiple cell types, such as cancer cells, MDSCs, macrophages and NK cells." (PMID 38713229, 2024). "Our data highlighted a significant enrichment of certain cellular adhesion molecules, including MCAM, EpCAM, ICAM-1, EGFR, and ALCAM, in cancer EVs relative to hTERT-immortalized MSC EVs." (PMID 38786083, 2024). "By modulating the sialylation of melanoma cell adhesion molecule (MCAM), ST6GAL1 inhibits the migration and invasion of HCC cells, showcasing novel avenues through which glycosylation can influence cancer progression." (PMID 38997696, 2024). "We analyzed the association between clinical-pathological characteristics and the expression of NOX1, ADAM17, and MCAM mRNA in three datasets (GSE39582, The Cancer Genome Atlas, and PETACC3)." (PMID 38137406, 2023). "CD146 (or melanoma cell adhesion molecule, MCAM) is well-studied for its important role in development, cell migration, immunology, angiogenesis, cancer progression, and myogenesis." (PMID 31828070, 2019). "First we approached the established signalling pathways downstream of MCAM: it is known to induce DVL2 and C-JUN phosphorylation in cancer cells and its knockdown leads to the induction of canonical WNT pathway." (PMID 28923978, 2017). "From this view, the highest value targets are MCAM and GPC2, which are expressed in the Top 25 for eight different cancers." (PMID 23251904, 2012). "Furthermore, we downloaded and statistically analyzed MCAM and UNC5A expression, as well as immunotherapy score data from TCGA and The Cancer Immunome Atlas (TCIA) databases respectively." (PMID 41407823, 2025). "These well-differentiated cancers, which retain some structural and functional characteristics of normal gastric epithelium, showed no detectable MCAM staining, suggesting that MCAM is not involved in the early or less aggressive stages of GC progression." (PMID 40924339, 2025).